TGFB1I1 (transforming growth factor beta 1 induced transcript 1)
Description:
Functions as a molecular adapter coordinating multiple protein-protein interactions at the focal adhesion complex and in the nucleus. Links various intracellular signaling modules to plasma membrane receptors and regulates the Wnt and TGFB signaling pathways. May also regulate SLC6A3 and SLC6A4 targeting to the plasma membrane hence regulating their activity. In the nucleus, functions as a nuclear receptor coactivator regulating glucocorticoid, androgen, mineralocorticoid and progesterone receptor transcriptional activity. May play a role in the processes of cell growth, proliferation, migration, differentiation and senescence. May have a zinc-dependent DNA-binding activity.
Synonyms: Hic-5; ARA55; TSC-5; HIC5
Tractability: PROTAC: ubiquitination databases record sites on it.
Gene: Protein-coding gene on chromosome 16 (31,471,585 to 31,478,727, forward strand). Ensembl gene ENSG00000140682.
Subcellular location: Cell junction, focal adhesion; Nucleus matrix; Cytoplasm, cytoskeleton
Subcellular location (Human Protein Atlas): Focal adhesion sites; Cytosol; Vesicles
Gene Ontology:
Molecular function: I-SMAD binding; nuclear androgen receptor binding; protein binding; Roundabout binding; transcription coactivator activity
Biological process: positive regulation of DNA-templated transcription; positive regulation of epithelial to mesenchymal transition; positive regulation of transforming growth factor beta receptor signaling pathway; positive regulation of ubiquitin-dependent protein catabolic process; cell adhesion; endothelial cell migration; negative regulation of cell population proliferation; substrate adhesion-dependent cell spreading
Cellular component: extracellular matrix; focal adhesion; cell-cell junction; cytoskeleton; nuclear matrix
Genetic constraint (gnomAD): Loss-of-function variants: 33 observed, 50.21 expected, observed/expected ratio (o/e) 0.66, 90% interval 0.5 to 0.88. The upper end of that interval is the gene's LOEUF score, 0.88, which puts it in group 3 of 6, group 1 being the genes least tolerant of losing a copy. Missense variants: 577 observed, 622.11 expected, observed/expected ratio (o/e) 0.93, 90% interval 0.87 to 0.99. Synonymous variants: 236 observed, 257.52 expected, observed/expected ratio (o/e) 0.92, 90% interval 0.82 to 1.02.
Homologues: Orthologues: macaque TGFB1I1 (98% identical), chimpanzee TGFB1I1 (97% identical), guinea pig TGFB1I1 (95% identical), rat Tgfb1i1 (92% identical), mouse Tgfb1i1 (91% identical), pig TGFB1I1 (90% identical), dog SLC5A2 (81% identical), tropical clawed frog tgfb1i1 (54% identical), Drosophila melanogaster Pax (46% identical), Caenorhabditis elegans pxl-1 (36% identical), Drosophila melanogaster CG34325 (16% identical), Drosophila melanogaster CG30178 (15% identical), and 4 more. Paralogues in human: PXN (52% identical), LPXN (40% identical).
Diseases named in the same sentence as TGFB1I1 in open-access papers:
TGFB1I1 is named in the same sentence as 58 diseases in open-access papers, as found by Europe PMC text mining. Sharing a sentence is not in itself a finding about the gene and the disease. The quoted sentences say what the papers report.
breast carcinoma (11 papers, 2011 to 2024). "SPOCK1 and TGFB1I1 (also called hydrogen peroxide-inducible clone 5) are induced by TGF-β and promote breast cancer cell invasion." (PMID 33420367, 2021).
liver fibrosis (10 papers, 2019 to 2025). "Previous studies revealed that TGFB1I1 acted as key roles in a variety of pathological processes, including liver fibrosis, atherosclerosis, tumorigenesis and progression." (PMID 36505846, 2022). "TGFβ-1-induced transcript 1 protein (TGFβ1i1), also named as hydrogen peroxide-inducible clone-5 (Hic-5), inhibits the activation of HSCs and liver fibrosis through reducing the TGF-β/Smad2 signaling by upregulation of Smad7." (PMID 34440218, 2021).
prostate carcinoma (9 papers, 2011 to 2022). A carcinoma that arises from epithelial cells of the prostate gland. "TGFB1I1 (Transforming growth factor beta 1 induced transcript 1) is a coactivator of the androgen receptor, it is known to be associated with prostate cancer, and it can induce EMT, at least in astrocytomes." (PMID 32252623, 2020). "We further identified increased promoter DMR methylation in prostate cancer correlating with decreased expression of mRNA and protein expression also on FBXO2, TGFB1I1, and TNS1." (PMID 29563510, 2018).
esophageal squamous cell carcinoma (4 papers, 2019 to 2024). Esophageal squamous cell carcinoma (ESCC) is a type of esophageal carcinoma (EC) that can affect any part of the esophagus, but is usually located in the upper or middle third. "TGFB1I1 have been verified to be acted as an oncogene in several cancers, including esophageal squamous cell carcinoma, breast tumor, ovarian cancer, and osteosarcoma." (PMID 36505846, 2022).
asthma (3 papers, 2022 to 2025). "Single-cell RNA-seq (scRNA-seq) analysis of cells isolated from asthma patients revealed elevated TGFB1I1 expression in basal airway epithelial cells and confirmed its link to bronchoconstriction." (PMID 40343342, 2025). "Significant DMPs fall within genes involved in the TFG-β related pathways (e.g. BMP2, FLCN, ING2, PMEPA1, PRDM16, TGFB1I1 and TGFBR3), in line with previous studies that reported an association between these genes and the increased asthma risk." (PMID 35619695, 2022). "Importantly, the extent of allergen-induced TGFB1I1 expression was significantly greater in individuals with asthma who underwent bronchoconstriction than in allergic individuals without asthma." (PMID 41387449, 2025). "To further establish a mechanistic link between TGFB1I1 induction in our in vitro system and its clinical relevance during bronchoconstriction in asthma exacerbations, we employed a novel approach by annotating TGFB1I1 expression using scRNA-seq data from published human asthma exacerbation studies." (PMID 40343342, 2025). "In addition, allergen-induced TGFB1I1 expression was also detected in allergic controls, albeit to a lesser extent than in asthma patients, suggesting that additional allergy-mediated factors may contribute to the induction of Hic-5." (PMID 41387449, 2025).
colorectal cancer (3 papers, 2019 to 2023). A primary or metastatic malignant neoplasm that affects the colon or rectum. "Moreover, the high expression of TGFB1I1 suggested the sensitivity of advanced colorectal cancer to chemotherapy." (PMID 36341390, 2022).
diabetes (3 papers, 2024 to 2026). "Through this approach, we uncovered a previously unrecognized role of hUCMSCs in modulating metabolic reprogramming and EndMT and identified the Tgfb1i1/Rock1 axis as a key regulator driving the loss of endothelial characteristics in diabetes." (PMID 41535231, 2026). "In addition to the increased expression of the ECM protein COL4A6, LAMB2, and HIC5 (encoded by Tgfb1i1) are also present in the livers of mice with late-stage diabetes and HFD/STZ." (PMID 39494341, 2024). "Our study extends the current understanding by demonstrating that hUCMSCs attenuate diabetes-induced EndMT through suppression of the Tgfb1i1/ROCK1 pathway." (PMID 41535231, 2026). "Collectively, our findings reveal a novel molecular mechanism through which hUCMSCs may reduce the inflammatory microenvironment via interactions with Tgfb1i1 and Rock1, thereby mitigating EndMT progression and aortic remodeling in diabetes." (PMID 41535231, 2026).
prostate tumors (3 papers, 2015 to 2023). "SPP1 and CLDN8 were upregulated in prostate tumor tissues, whereas COL4A6, RND3, DPT, EFS, and TGFB1I1 were downregulated." (PMID 37251946, 2023).
astrocytomas (2 papers, 2014 to 2022). "TGFB1I1 was found to be associated with TGFβ stimulated EMT process in the malignant progression of astrocytomas." (PMID 36341390, 2022). "In addition, TGFB1I1 might be associated with subtype transition and could be used as serviceable marker for mensenchymal astrocytoma." (PMID 25333259, 2014). "The RNA and protein levels of TGFB1I1 were the highest in mesenchymal astrocytomas than others subtypes (neural, proneural and classical)." (PMID 25333259, 2014). "Studies in vitro and in vivo using TGF-β1 and TGFB1I1 shRNA demonstrated that TGFB1I1 is required for TGF-β stimulated EMT that contributes to malignant progression of astrocytomas." (PMID 25333259, 2014). "In our data, the RNA and protein levels of TGFB1I1 were significantly increased along with increasing astrocytoma grades and high expression of TGFB1I1 indicates a poor survival in patients with astrocytomas." (PMID 25333259, 2014). "Our data demonstrates that TGFB1I1 is required for TGF-β stimulated EMT that contributes to malignant progression of astrocytomas." (PMID 25333259, 2014). "The fact that high expression of TGFB1I1 indicated a poor survival outcome suggests that TGFB1I1 might play important role in malignant progression of astrocytomas by driving cell invasion and migration." (PMID 25333259, 2014). "Analysis of TGFB1I1 expression by IHC in independent tissue microarrays (5 NBTs, 64 AIIs and 34 AIIIs) provided a further level of evidence supporting the key role of TGFB1I1 in malignant progression of astrocytomas." (PMID 25333259, 2014). "More importantly, the up-regulated genes in astrocytomas mostly enriched in EMT associated signaling pathways (actin cytoskeleton, adhesion molecules and TGF-β signaling), suggesting that TGFB1I1-inducible EMT might be involved in the malignant progression of astrocytomas." (PMID 25333259, 2014).
bladder cancer (2 papers, 2019 to 2023). "IRF5 (p=0.055), CCN1 (p=4.1e-08), MYC (p=0.039), POU5F1 (p=0.027), and TGFB1I1 (p=6.5e-08) were significantly differentially expressed at different stages of bladder cancer." (PMID 37433010, 2023). "As such, COL5A1, COL8A1 and TGFB1I1 can serve as the prognosis biomarkers for patients of bladder cancer." (PMID 30723390, 2019). "Except for TGFB1I1, others were significant in distinguishing low and high stage of bladder cancers(P < 0.05)." (PMID 30723390, 2019). "Similarly, in TCGA database bladder cancer samples, CCN1 (p=7.9e-07), MYC (p=0.0043), POU5F1 (p=0.021), and TGFB1I1 (p=6.0e-05) had significant differences in bladder cancer high-grade and low-grade samples, in addition to IRF5 (p=0.2)." (PMID 37433010, 2023).
dyslipidemia (2 papers, 2020 to 2022). "TGFB1I1, VNN1, HLADRB4, and CXCL8 genes were differentially expressed in lymphocytes and monocytes of subjects with poorly controlled diabetes mellitus, dyslipidemia, and periodontitis in comparison with controls." (PMID 36233348, 2022).
gastric cancer (2 papers, 2022). A primary or metastatic malignant neoplasm involving the stomach. "Finally, we verified that TGFB1I1, TGFBR1, SMAD9 and SMAD4 are low expressed in gastric cancer by immunohistochemistry at the protein level, and RCAN2 is also low expressed in gastric cancer." (PMID 36483555, 2022).
periodontitis (2 papers, 2020 to 2022). An acute or chronic inflammatory process that affects the tissues that surround and support the teeth. "The validation analyses using RT-qPCR showed that four genes were differentially expressed in subjects with poorly controlled T2DM plus DL plus periodontitis compared to HS (TGFB1I1, VNN1, HLADRB4 and CXCL8)." (PMID 36233348, 2022).
Cirrhosis (1 paper, 2022). A chronic disorder of the liver in which liver tissue becomes scarred and is partially replaced by regenerative nodules and fibrotic tissue resulting in loss of liver function. "We found them to be upregulated in cirrhosis represented by the upregulation of PGDFRB, TGFB1 (TGF‐β1), TGFB1I1 (TGF‐β1 induced transcript 1 protein), TGFBI (TGF‐β induced protein ig‐h3), LTBP1, LTBP2, LTBP4, and ENG (transmembrane accessory receptor for TGF‐beta signaling)." (PMID 35579278, 2022).
COVID-19 (1 paper, 2025). A disease caused by infection with severe acute respiratory syndrome coronavirus 2. "Although not significantly different from that in the PLWH group, the level of TGFB1I1 in PLWH with COVID-19 was significantly lower than that in the HC group." (PMID 40568587, 2025).
fungal infection (1 paper, 2025). "There is further evidence of tissue remodeling and fibrosis with transforming growth factor beta-1-induced transcript 1 protein increased + 7.06 fold, indicating that TGF-β could drive fibrosis following fungal infection." (PMID 40665229, 2025).
glioma (1 paper, 2014). A benign or malignant brain and spinal cord tumor that arises from glial cells (astrocytes, oligodendrocytes, ependymal cells). "The invasive biomarkers of gliomas, MMP-2 and MMP-9, have also markedly positive correlation with TGFB1I1." (PMID 25333259, 2014).
hypospadias (1 paper, 2024). Hypospadias is the displacement of the urethral meatus on the ventrum of the penis. "It has been demonstrated that the expression of TGFB1I1 and other pro-angiogenic growth factors was significantly reduced in the GT of DBP-induced hypospadias rats, ultimately resulting in impaired angiogenic capacity." (PMID 39698037, 2024).
Sepsis (1 paper, 2023). Sepsis is defined as life-threatening organ dysfunction caused by a dysregulated host response to infection. "sepsis was associated with the C11_Plate cluster, and ESAM, HBG2, MMRN1, PF4V1, SAMD14, SELP, and TGFB1I1 may be important in this context." (PMID 37919720, 2023).
tumor (25 papers, 2014 to 2025). "A coexpression network analysis described the TGFB1I1 mRNA which is a coactivator of the AR that is associated with PCa cell differentiation, and decreased gene expression was observed to be associated with tumor progression." (PMID 34737889, 2021). "U87 control and TGFB1I1 shRNA transfected U87 cells were injected into the brains of a total of 20 nude mice (n=10 per group), and tumor formation was examined after 25 days." (PMID 25333259, 2014). "The protein expression of TGFB1I1 was gradually increasing with increasing tumor grades (NBT vs AII at p=0.003; AII vs AIII at p=0.003) (Figure-4A and B)." (PMID 25333259, 2014). "Finally, we examined genes’ expression between low and high tumor stage by the Wilcoxon test(P < 0.05), TGFB1I1 was excluded." (PMID 30723390, 2019). "Tumor volume with the TGFB1I1 shRNA was significantly smaller than did control mice (Figure-6B)." (PMID 25333259, 2014). "TGFB1I1, Transforming Growth Factor β 1 Induced Transcript 1, a multifunctional cytokine that regulates cell proliferation, differentiation, and production of the extracellular matrix, has an effect on development, wound healing, organ fibrosis, tumor generation, and metastasis." (PMID 36833431, 2023). "However, TGFB1I1 was meaningless in revealing tumor stage and was excluded." (PMID 30723390, 2019). "Consequently, the unique upregulation of TGF‐beta family genes TGFB1, TGFBR2, TGFBI, TGFB1I1, and TGFB3 in S‐ECM could be due to increased production of TGF‐beta by CAFs in the tumor microenvironment." (PMID 36637997, 2023).
cancer (20 papers, 2011 to 2025). A tumor composed of atypical neoplastic, often pleomorphic cells that invade other tissues. "TGFB1I1 has also been shown to function as an oncogene by inducing EMT to promote invasion in cancer cells as well as in normal breast epithelial cells." (PMID 25333259, 2014). "Several members of the NCOA and bromodomain families were more highly expressed in the cancer cells, while CAV1, FHL2, MED1, and Hic-5 (TGFB1I1) were all higher in the fibroblasts." (PMID 37435460, 2022).
TGFB1I1 also shares sentences with these, for which no sentence is quoted: hepatocellular carcinoma (6 papers); osteosarcoma (4); breast tumor (3); melanoma (3); osteoarthritis (3); ovarian carcinoma (3); cholangiocarcinoma (2); chronic pancreatitis (2); endometriosis (2); fatty liver (2); glioblastoma (2); Glomerular sclerosis (2); infection (2); metabolic dysfunction-associated steatohepatitis (2); pancreatic cancer (2); abdominal aortic aneurysm (1); allergic asthma (1); Allergy (1); Arthritis (1); atherosclerosis (1); benign prostatic hyperplasia (1); brain diseases (1); brain tumors (1); colorectal tumor (1); endometritis (1); esophageal cancer (1); glomerulonephritis (1); heart failure (1); infectious disease (1); lymph node metastasis (1).
A further 7 diseases each share a sentence with TGFB1I1 in 1 paper.